PCSK9 (proprotein convertase subtilisin/kexin type 9)
Diseases named in the same sentence as PCSK9 in open-access papers (continued):
Sharing a sentence is not in itself a finding about the gene and the disease.
atherosclerosis (continued). "As expected, genetic inhibition of PCSK9 was associated with lower levels of LDL-C and ApoB, less subclinical atherosclerosis, lower risk of MOVE, including ischaemic stroke, and directionally concordant effects on risk of FOVE and MCE." (PMID 38198221, 2024). "Another facet of the relationship among inflammation, PCSK9, and atherosclerosis relates to oxidized low-density lipoproteins (oxLDL)." (PMID 39150672, 2024). "PCSK9 inhibition is, therefore, a rational therapeutic target in treating patients suffering from atherosclerosis." (PMID 38469142, 2024). "There are several studies based on different imaging methods aiming to support that PCSK9 inhibitors reduce arterial wall inflammation and atherosclerosis burden by modifying atherosclerotic plaque characteristics." (PMID 36986246, 2023). "In many recent related studies, PCSK9 is closely related to atherosclerosis, platelet aggregation, thrombogenesis, and vascular aging." (PMID 38273837, 2023). "PCSK9 blocking agents reduce systemic levels of total cholesterol and LDL, affecting the risk of atherosclerosis but also reducing the supply of cholesterol by cancer cells through the enhancement of apolipoprotein E receptor, CD36, β-secretase 1, and others." (PMID 36900189, 2023). "To this end, we designed a treatment strategy on an established pathological model with ectopic proprotein convertase subtilisin/kexin type 9 (PCSK9) expression and Western diet feeding, which effectively induced hyperlipidemia and atherosclerosis." (PMID 39872857, 2023). "In the atherosclerotic mouse model, Pcsk9 overexpression promotes atherosclerosis, whereas deletion is protective." (PMID 38093957, 2023). "Although PCSK9 was initially linked to elevated LDL-C, recent studies have found its involvement in atherosclerosis, viral infections, immune activation, and tumor progression." (PMID 37350960, 2023). "In the current study we find that PF-06409577 reduces atherosclerosis in ApoE−/− and PCSK9 over-expression mouse models through a pathway requiring the AMPK β1 isoform." (PMID 38026185, 2023). "LRP5 and LRP6, as coreceptors of PCSK9, promote atherosclerosis by activating the Wnt/β-catenin signaling pathway, resulting in significant proliferation of VSMCs and decreased anti-inflammatory macrophages." (PMID 36970356, 2023). "In recent years, many studies have explored the role of PCSK9 in atherosclerosis; however, the predictive role of PCSK9 in cardiovascular outcomes remains controversial." (PMID 38115042, 2023). "With the in-depth study of PCSK9, more scholars have discovered its mechanism of raising blood lipids, accelerating the formation of atherosclerosis and participating in the formation of thrombosis." (PMID 38273837, 2023). "In general, PCSK9 can affect the progression of atherosclerosis by raising blood lipids and atherosclerotic plaque accumulation." (PMID 38273837, 2023). "Here, we utilized a vascular microphysiological system to test the effect of PCSK9 activation or repression on the initiation of atherosclerosis and to screen the efficacy of a small molecule PCSK9 inhibitor." (PMID 37854060, 2023). "It has been clearly established that PCSK9 plays a crucial role in the development of atherosclerosis." (PMID 36911736, 2023). "In this study, we explored the utility of the established TEBV platforms to study the effect of PCSK9 activation or repression on vascular inflammation and the initiation of atherosclerosis." (PMID 37854060, 2023). "Mechanistically, PCSK9 plays a key role in platelet aggregation and adherence to endothelial cells, endothelial dysfunctions, and atherosclerosis." (PMID 36900189, 2023). "In this study, by utilizing the significant advantages of nano-materials, a biomimetic nanoliposome loading with Evolocumab (Evol), a PCSK9 inhibitor, was designed to alleviate atherosclerosis." (PMID 37208681, 2023).
atherosclerosis (continued). "We have demonstrated that PCSK9 activation can exacerbate the local inflammatory response in vascular cells in an in vitro model of early-stage atherosclerosis." (PMID 37854060, 2023). "In this review, we have looked into mechanisms through which PCSK9 can contribute to the development of atherosclerosis." (PMID 36831039, 2023). "A slight positive correlation between the concentration of PCSK9-Lp(a) complexes and the absolute level of monocytes was obtained (r = 0.20, p = 0.002) in the patients with atherosclerosis due to the intermediate monocyte subsets (r = 0.33, p = 0.04)." (PMID 37511689, 2023). "Ddr1WT (Ddr1flox/flox, Cdh5-CreERT2−) and Ddr1iECKO mice were injected once with adeno-associated-virus-8 (AAV8)-overexpressing PCSK9 (AAV8-PCSK9) via the tail vein and fed on a Western diet to induce hyperlipidemia, a potent risk factor for atherosclerosis." (PMID 37833282, 2023). "According to regression analysis, both the PCSK9-Lp(a) complexes concentration and BMI were related to the absolute number of blood monocytes in patients with atherosclerosis." (PMID 37511689, 2023). "PCSK9 inhibitors have been shown to be beneficial in the treatment of patients with atherosclerosis and ASCVDs." (PMID 36970356, 2023). "Accurate mechanisms of anti-inflammatory effects of PCSK9 inhibition in atherosclerosis are still poorly elucidated." (PMID 36986246, 2023). "Further studies are required to determine the pathogenetic contribution of PCSK9-Lp(a) complexes to the development of atherosclerosis." (PMID 37511689, 2023). "Proprotein convertase subtilisin/kexin type 9 (PCSK9) is considered a new biomarker for atherosclerosis, but its ability to predict cardiovascular outcomes has been controversial." (PMID 38115042, 2023). "Platelet activation and proprotein convertase subtilisin kexin 9 (PCSK9) play pivotal roles in the progression of atherosclerosis to cardiovascular events." (PMID 37892538, 2023). "In our point, this study, which expanded the mechanism of PCSK9 inhibition on atherosclerosis therapy, demonstrated that the constructed (Lipo + M)@E NPs provide a promising option for the treatment of atherosclerosis." (PMID 37208681, 2023). "It is believed that PCSK9, in addition to regulating LDL cholesterol in the plasma, is associated with procoagulation, thus enhancing the development of atherosclerosis." (PMID 36768292, 2023). "To study the effects of PCSK9 activation and repression on atherosclerosis progression in the vascular microenvironment, we fabricated TEBVs using WT, P+, and P− viSMCs and viECs." (PMID 37854060, 2023). "This was supported by our finding that arterial Tie2 protects from atherosclerosis in a Western diet mouse atherosclerosis model in which the LDL receptor is downregulated by AAV-mediated expression of an activated form of Pcsk9." (PMID 37476204, 2023). "These suggest the beyond cholesterol-lowering beneficial effects of PCSK9 inhibitors in impeding atherogenesis during the initial phase of atherosclerotic plaque development, hence their potential role in preventing atherosclerosis-related complications." (PMID 36982171, 2023). "Although Il1a knock out animals show greatly reduced atherosclerosis development compared with PCSK9-WT animals, macrophage infiltration per plaque is unchanged." (PMID 37701434, 2023). "A new key driver of the atherosclerosis process is proprotein convertase subtilisin/kexin type 9 (PCSK9)." (PMID 36900189, 2023).
atherosclerosis (continued). "In this work, we developed a model of PCSK9 activation in combination with a three-dimensional blood vessel model of early-stage atherosclerosis." (PMID 37854060, 2023). "Next, the researchers studied the effect of PCSK9 inhibitors on vascular inflammation and atherosclerosis." (PMID 38093957, 2023). "PCSK9, which is closely related to atherosclerosis, is significantly expressed in vascular smooth muscle cells (VSMCs)." (PMID 37208681, 2023). "In this review, we will summarize the available data on the role of PCSK9 in the development and progression of atherosclerosis." (PMID 36831039, 2023). "Experimental studies have indicated that early intervention in the phenotypic transformation of VSMCs can improve the progression and prognosis of atherosclerosis by inhibiting PCSK9." (PMID 37208681, 2023). "Experimentally, it was also found that an increased concentration of PCSK9 significantly accelerated the apoptosis of endothelial cells and reduced endothelial function, which created conditions for the development of atherosclerosis." (PMID 36768292, 2023). "Mostly secreted in the liver, PCSK9 is also expressed in the arterial wall, where it can influence local hemostasis and atherosclerosis." (PMID 35326219, 2022). "Given that macrophages are relevant components of the lipidic and inflammatory environment of atherosclerosis, we studied the effects of PCSK9 treatment on human macrophages." (PMID 36012389, 2022). "The pro-inflammatory cytokines TNF-α and IL-1β are known to contribute to the development of atherosclerosis and foam cell formation, further evidencing the detrimental role of PCSK9 in this pathology." (PMID 36012389, 2022). "The PCSK9 appears to be a promising biomarker in the game of atherosclerosis; in fact, the PCSK9 plasma levels have been suggested to be linked with atherosclerosis progression by lipid and non-lipid pathways." (PMID 35454151, 2022). "In vitro, primary cells from mouse aortic endothelial cells (MAEC) and mouse cardiac endothelial cell (MCEC) lines have been successfully used for the investigation of PCSK9 in atherosclerosis development." (PMID 36005422, 2022). "Investigation into the regulatory function of PCSK9 in atherosclerosis showed that PCSK9 activated NF-κB signaling to promote inflammation." (PMID 35832650, 2022). "For example, the Ossabaw mutant pig animal model can be used to investigate the effect of PCSK9 on atherosclerosis." (PMID 36005422, 2022). "In any case though, our studies show that PCSK9 in apoB-depleted plasma does affect the atheroprotective properties of HDL indicating a novel role of PCSK9 in atherosclerosis." (PMID 36067830, 2022). "Dennd5b−/− mice are resistant to PCSK9 effects on plasma lipoproteins and develop less atherosclerosis than wild type mice." (PMID 36243100, 2022). "Atherosclerosis is currently treated primarily with statins, ezetimibe, and proprotein convertase subtilisin kexin type 9 (PCSK9) inhibitors to decrease plasma cholesterol." (PMID 35917178, 2022). "Our data suggest that PCSK9 acts as an activator of NLRP3, revealing a new mechanism for NLRP3 involvement in atherosclerosis and underlining the importance of the inflammasome in this pathology." (PMID 36012389, 2022).
atherosclerosis (continued). "Quercetin prevents the development of atherosclerosis in ApoE−/− mice by regulating the expression of PCSK9, CD36, PPARγ, LXRα, and ABCA1." (PMID 35845584, 2022). "Experimentally, overexpression of suPAR in a murine model of atherosclerosis using Pcsk9-AAV led to a 2-fold increase in atherosclerotic plaque size with large necrotic cores and macrophage infiltration in suPARTg mice compared with WT mice." (PMID 36194491, 2022). "Overall, this creates a new paradigm in the comprehension of PCSK9 function in Mφ metabolism and atherosclerosis progression." (PMID 36012389, 2022). "The plasma levels of PCSK9 correlate with the probability of future adverse cardiovascular events and atherosclerosis progression." (PMID 36012389, 2022). "On the other hand, statin remains the first-line and mainstream lipid-lowering agent for patients with atherosclerosis, but this classical medication inevitably drives up levels of PCSK9 within the circulation." (PMID 36291690, 2022). "Beyond its lipid-lowering effect, accumulative evidence has shown the implication of PCSK9 in preventing and slowing down atherosclerosis disease progression by being involved in platelet activation." (PMID 36005422, 2022). "Proprotein convertase subtilisin/kexin type 9 (PCSK9) plays a major role in cholesterol metabolism and atherosclerosis by modulating the circulating levels of low-density lipoprotein (LDL), the key molecule that transports cholesterol in the blood." (PMID 36012389, 2022). "In this study, we examined cortical haemodynamics in mouse preparations that modelled Alzheimer’s disease (J20-AD) and atherosclerosis (PCSK9-ATH) between 9 and 12 m of age." (PMID 35014950, 2022). "The pro-inflammatory role of PCSK9 in atherosclerosis progression has been confirmed both by experimental evidence and clinical data." (PMID 35252378, 2022). "As a result, we believe that additional research using a bigger sample size is necessary to definitively establish the effect of PCSK9 inhibitor therapy on proinflammatory cytokines and novel atherosclerosis markers." (PMID 35890100, 2022). "Taken together, our results demonstrate that, in addition to being a therapeutic target, PCSK9 can serve as a biomarker, underscoring the importance of PCSK9 inhibitors in the treatment of atherosclerosis." (PMID 36012389, 2022). "Recent studies have proven that PCSK9 promotes the development of atherosclerosis not only through the mechanism of increased plasma LDL-C concentrations but also through direct action on the cells that form the artery walls and atherosclerotic plaques." (PMID 35566668, 2022). "PCSK9 inhibitors are mainly used in clinical hyperlipidemia, atherosclerosis (As), and related ischemic cardiovascular diseases with significant effects and can be used as a substitute for statins and ezetimibe." (PMID 36230934, 2022). "In vivo, the direct relationship between PCSK9 and atherosclerosis was investigated by utilizing Apolipoprotein E (ApoE) deficient mice." (PMID 36005422, 2022). "As is well-known, the WBCC is a traditional marker of inflammation and either inflammation or PCSK9 was considerably connected with atherosclerosis in populations with different levels of baseline risks." (PMID 35252378, 2022). "In this sense, and because Mφ are key players in atherosclerosis progression, the knowledge of PCSK9-dependent effects on Mφ is of paramount importance." (PMID 36012389, 2022). "The aim of this review is to summarize the recent reports concerning the regulatory role of PA on PCSK9 plasma levels, highlighting the beneficial role of regular exercise on the prevention of atherosclerosis and overall CV health." (PMID 36093150, 2022).
atherosclerosis (continued). "These pathways are relevant in the outcome of atherosclerosis and highlight the relevance of PCSK9 as a therapeutic target for the treatment of cardiovascular diseases." (PMID 36012389, 2022). "More importantly, it is believed that PCSK9, in addition to regulating the level of LDL-C in the plasma, is associated with procoagulation, enhancing the development of atherosclerosis." (PMID 35566668, 2022). "The roles of PCSK9 in regulating the inflammation pathway in atherosclerosis-induced cardiovascular diseases have been well addressed in a previous review." (PMID 35207479, 2022). "PCSK9 inhibitors have significant efficacy in hyperlipidemia, atherosclerosis, and other diseases, with many reports highlighting the potential therapeutic effects of PCSK9 inhibitors in treating sepsis, tumors, and some viral infections, among other diseases." (PMID 36230934, 2022). "Atherosclerosis models exhibited that PCSK9 inhibition restrains atherosclerotic progression and improves plaque morphology." (PMID 35252378, 2022). "Taken together, these findings indicated that the PCSK9 protein is an important target for the prevention and treatment of atherosclerosis." (PMID 36077166, 2022). "PCSK9 plays an important role in inflammation and serves as an inflammatory mediator in atherosclerosis." (PMID 36330745, 2022). "Accordingly, collective studies have demonstrated that PCSK9 directly promotes atherosclerosis by being involved in atherosclerotic inflammation." (PMID 35207479, 2022). "The purpose of this review is to highlight the role of exercise training on PCSK9 plasma levels, as a prevention strategy against atherosclerosis." (PMID 36093150, 2022). "Accumulating evidence from basic research shows that PCSK9 promotes vascular inflammation through upregulating classical pro-inflammatory pathways involved in atherosclerosis, such as TLR4/MyD88/NF-κB and NLRP3 inflammasomes." (PMID 36291690, 2022). "Another rabbit model that has been used to research about PCSK9-induced atherosclerosis is a Yucatan minipig, which can express D374Y-PCSK9." (PMID 36005422, 2022). "Their study was the first to give a hint about a link between high PCSK9 levels, platelets, atherosclerosis, and cardiovascular disorders." (PMID 35207479, 2022). "PCSK9 has emerged in recent years as an important target in the management of atherosclerosis and has been targeted by monoclonal antibody drugs (evolocumab and alirocumab) [22••] and inclisiran, leading to substantial reductions in LDL-C." (PMID 34468873, 2021). "The discovery of a serine protease protein known as proprotein convertase subtilisin kexin 9 (PCSK9) has paved a way for the development of new therapeutic agents to combat atherosclerosis." (PMID 34443682, 2021). "Evidence also shows that PCSK9 can enhance the production of pro-inflammatory cytokines that play an important role in atherosclerosis plaque inflammation." (PMID 34869702, 2021).